TECTB (tectorin beta)
Description:
One of the major non-collagenous components of the tectorial membrane (By similarity). The tectorial membrane is an extracellular matrix of the inner ear that covers the neuroepithelium of the cochlea and contacts the stereocilia bundles of specialized sensory hair cells. Sound induces movement of these hair cells relative to the tectorial membrane, deflects the stereocilia and leads to fluctuations in hair-cell membrane potential, transducing sound into electrical signals.
Tractability: Antibody: UniProt places it where antibodies can reach, with high confidence; its Gene Ontology location is reachable by antibodies, with high confidence; UniProt predicts a signal peptide or a membrane-spanning region.
Gene: Protein-coding gene on chromosome 10 (112,283,400 to 112,305,038, forward strand). Ensembl gene ENSG00000119913.
Subcellular location: Cell membrane; Secreted, extracellular space, extracellular matrix
Pathways (Reactome):
Metabolism of proteins: Post-translational modification: synthesis of GPI-anchored proteins
Gene Ontology:
Molecular function: extracellular matrix structural constituent
Cellular component: cell surface; extracellular region; plasma membrane; extracellular matrix
Genetic constraint (gnomAD): Loss-of-function variants: 42 observed, 43.26 expected, observed/expected ratio (o/e) 0.97, 90% interval 0.76 to 1.26. The upper end of that interval is the gene's LOEUF score, 1.26, which puts it in group 5 of 6, group 1 being the genes least tolerant of losing a copy. Missense variants: 398 observed, 424.43 expected, observed/expected ratio (o/e) 0.94, 90% interval 0.86 to 1.02. Synonymous variants: 169 observed, 165.29 expected, observed/expected ratio (o/e) 1.02, 90% interval 0.9 to 1.16.
Homologues: Orthologues: chimpanzee TECTB (100% identical), guinea pig TECTB (95% identical), rabbit TECTB (95% identical), mouse Tectb (94% identical), rat Tectb (94% identical), dog TECTB (93% identical), pig TECTB (92% identical), macaque TECTB (86% identical), tropical clawed frog tectb (66% identical), zebrafish tectb (52% identical). Paralogues in human: ZPLD1 (29% identical), GP2 (20% identical), OIT3 (18% identical), UMOD (18% identical), UMODL1 (18% identical).
Diseases named in the same sentence as TECTB in open-access papers:
TECTB is named in the same sentence as 4 diseases in open-access papers, as found by Europe PMC text mining. Sharing a sentence is not in itself a finding about the gene and the disease. The quoted sentences say what the papers report.
sensorineural hearing loss (1 paper, 2025). "AS a candidate gene for hearing loss, TECTB may act downstream of Gata3 in cochlear supporting cells, with altered expression contributing to sensorineural deafness in hypoparathyroidism, sensorineural hearing loss, and renal disease (HDR) syndrome." (PMID 40901670, 2025). "We also examine the contributions of genes such as TECTA, TECTB, and CEACAM16, whose mutations disrupt TM integrity and lead to sensorineural hearing loss." (PMID 40901670, 2025).
virus infection (1 paper, 2023). "Among these, only one protein was interesting relative to virus infection (TECTB)." (PMID 36830041, 2023).
TECTB also shares sentences with these, for which no sentence is quoted: hearing loss (1 paper); hepatocellular carcinoma (1).